MTOR (mechanistic target of rapamycin kinase)
Diseases named in the same sentence as MTOR in open-access papers (continued):
Sharing a sentence is not in itself a finding about the gene and the disease.
osteoarthritis (continued). "PI3K/Akt/mTOR signaling regulated autophagy in macrophages in the development of diabetic encephalopathy and, in particular, chondrocytes by inhibiting miR-20 in osteoarthritis." (PMID 33809718, 2021). "Protein expression levels of Akt, phosphorescent p-Akt, mammalian target of rapamycin (mTOR), and p-mTOR in the PI3K/Akt/mTOR signaling pathway were decreased in the IL-1β-induced SW1353 cells following scutellarein treatment of osteoarthritis." (PMID 34671661, 2021). "Previous literature has shown that Sirt3 has an important protective effect on the pathophysiology of osteoarthritis by inhibiting the PI3K/Akt/mTOR signaling pathway." (PMID 34095262, 2021). "It has been well documented in the literature that miR‐100‐5p‐abundant exosomes derived from infrapatellar fat pad mesenchymal stem cells (MSCs) protect articular cartilage and ameliorate gait abnormalities via inhibition of mTOR in osteoarthritis." (PMID 32307881, 2020). "Zhang et al21 reported depleting of mTOR up‐regulated autophagy and inhibited mice osteoarthritis development." (PMID 32862562, 2020). "The AKT/mTOR pathway was reported to reduce inflammatory response by modulating autophagy in osteoarthritis." (PMID 32760250, 2020). "More recently, miR-100-5p-abundant exosomes derived from infrapatellar fat pad MSCs have been shown to protect articular cartilage and ameliorate gait abnormalities by enhancing autophagy via targeted inhibition of mTOR in osteoarthritis." (PMID 32169098, 2020). "On the contrary, miR-100-5p-abundant exosomes derived from human infrapatellar fat pad mesenchymal stem cells protect articular cartilage via inhibition of mTOR in osteoarthritis which suggests a complex role for this fatty organ in knee/stifle degeneration." (PMID 31622367, 2019). "Dysregulation of mTOR signalling and autophagy is observed in multiple ARDs including neurodegenerative diseases, osteoarthritis and cardiovascular diseases." (PMID 30741380, 2019). "Local intra-articular injection of rapamycin(mTOR inhibitor) or cartilage-specific deletion of mTOR can delay articular cartilage degeneration in a murine model of OA or protect mice from osteoarthritis." (PMID 29435116, 2018). "This study shows the PI3K/AKT/mTOR signaling pathway is really a critical pathway for cellular autophagy and that Isorhy promotes autophagy in OA cells thought inhibiting the PI3K/AKT/mTOR signaling pathway precisely, thereby effectively alleviating the progression of osteoarthritis." (PMID 36864518, 2023). "Furthermore, SND1 silencing reduced AMPK and mTOR phosphorylation levels in knee joint cartilage tissues of osteoarthritis rat." (PMID 37749650, 2023). "Mice with hypomorphic mTOR have increased lifespan and reduced senescent marker p16INK4A expression, demonstrating the link between tissue degeneration and ageing, while mice with articular cartilage‐specific mTOR deletion are protected against osteoarthritis through enhancement of autophagy." (PMID 36869852, 2023). "Previous studies showed that AMPK/mTOR pathway had a major role in osteoarthritis progression." (PMID 37249294, 2023). "In addition, exosomes isolated from human infrapatellar fat pad derived-MSCs protect articular cartilage and ameliorate gait abnormalities due to osteoarthritis via inhibition of the mammalian target of rapamycin (mTOR)." (PMID 36714697, 2022). "Besides, some researchers found that four-octyl itaconate improves osteoarthritis by enhancing autophagy in chondrocytes via PI3K/AKT/mTOR signaling pathway inhibition." (PMID 36035226, 2022). "Exosomes with abundant miR‐100‐5p derived from infrapatellar fat pad MSCs could protect articular cartilage and ameliorate gait abnormalities by inhibition of mTOR expression in osteoarthritis." (PMID 32424968, 2020). "In addition, CCN3 is identified as a protective factor in cartilage by inhibiting the PI3K/AKT/mTOR pathway, alleviating the deterioration of osteoarthritis." (PMID 32455138, 2020).
osteoarthritis (continued). "Furthermore, miR-100-5p-abundant exosomes derived from fat pad MSCs was confirmed to protect articular cartilage via suppressing mTOR levels in osteoarthritis." (PMID 32178675, 2020). "Interestingly, by blocking mTOR signaling using rapamycin, several studies have shown a positive impact on chondrogenesis and in osteoarthritis." (PMID 30678371, 2019). "Other top hits for metformin included glucosamine, a compound used in the treatment of osteoarthritis, and car-damonin, a member of the anti-inflammatory chalcones found in plant-based foods, which inhibits mTOR and exhibits antitumor effects in vitro and in vivo." (PMID 29165314, 2017). "Since 2020, other keywords have shown notable bursts, indicating key areas of focus: “mTOR” and “induction” highlight the exploration of cellular growth and regulatory mechanisms; “cell death” underscores interest in apoptosis and related processes in osteoarthritis." (PMID 40988280, 2025). "Because it has been demonstrated that mTOR decreases autophagy targeting the mTOR signaling pathway results in increased autophagy signalling and secondary reduces apoptosis, articular cartilage degradation, and synovial fibrosis thus protecting from osteoarthritis." (PMID 30708978, 2019). "Bajijiasu can reduce metabolic decomposition and inflammatory response of osteoarthritis (OA) in vitro and in vivo, possibly by regulating AKT/mTOR/NF-κB signaling pathway to promote autophagy." (PMID 40375996, 2025). "For instance, we failed to explain the detailed mechanism through which ALA‐24A regulate AMPK/mTOR pathway and what's the direct target of ALA‐24A in osteoarthritis." (PMID 37249294, 2023). "In another study of osteoarthritis chondrocytes, ICA was believed to activate autophagy through activation of the PI3K/AKT/mTOR signaling pathway." (PMID 34847836, 2022). "In particular, mTOR inhibition by rapamycin or AMPK suppresses inflammatory diseases and osteoarthritis by regulating T-cell differentiation." (PMID 33668426, 2021). "Consequently, polydatin improved autophagy and apoptosis during osteoarthritis through suppressing the MAPK and phosphoinositide 3-kinases (PI3K)/Akt/mammalian target of rapamycin (mTOR) signaling pathway." (PMID 36235012, 2022). "In osteoarthritis, the downregulation of CDR1as can activate the AKT/mTOR signaling pathway." (PMID 35154259, 2021). "Recently, we found that SIRT3 could ameliorate osteoarthritis via regulating chondrocyte autophagy and apoptosis through the PI3K/Akt/mTOR pathway." (PMID 34646424, 2021). "In addition, various transcription factors and regulators involved in osteoarthritis progression include RUNX2 (Runt-related transcription factor 2), ADAMTS (a disintegrin and metalloproteinase with thrombospondin motifs), mTOR (mammalian target of rapamycin) and MMPs." (PMID 38235147, 2023). "Collectively, the present study indicates that Sox8 downregulation inhibits the PI3K/AKT/mTOR signaling pathway and increases the level of autophagy in MSU-induced impairment of chondrocytes in vitro and in vivo, making Sox8 a potential treatment target for gout-induced osteoarthritis." (PMID 36918540, 2023). "Expression of NOV, encoding a small secreted regulatory protein, was upregulated in responders; NOV overexpression attenuates the PI3K-Akt-mTOR pathway and decreases MMP production, while mice without NOV protein display an osteoarthritis-like disease." (PMID 33746955, 2021).
Cerebral ischemia (96 papers, 2014 to 2026). Restriction of arterial blood supply to the brain associated with insufficient oxygenation to support the metabolic requirements of the tissue. "A pivotal player in the PI3K/Akt/mTORC1 survival pathway, the mTOR protein is associated with neuroprotection in the context of cerebral ischemia through its role in the maintenance of neuronal homeostasis." (PMID 38582839, 2024). "In the context of the present work, it is noteworthy that brain ischemia causes regulation of mTOR signaling, which is known to be able to phosphorylate several residues of NBCe1, thereby altering its transport activity." (PMID 38067105, 2023). "Thence, the present study indicated that intermittent hypoxia preconditioning can aggravate the nerve injury of the global cerebral ischemia-reperfusion model, and the mechanism is associated with the activation of mTOR/autophagy pathway." (PMID 28177899, 2017). "We explored the role of mTOR/autophagy pathway in the aggravation of cerebral ischemia-reperfusion nerve injury caused by intermittent hypoxia." (PMID 28177899, 2017). "In the present study, we found intermittent hypoxia preconditioning can aggravate the nerve injury of the global cerebral ischemia-reperfusion model, and the mechanism is associated with the activation of mTOR/autophagy pathway." (PMID 28177899, 2017). "We hypothesized that upregulation of brain-derived neurotrophic factor (BDNF) expression and activation of Akt/mTOR/p70S6K signaling after ME could partially underlie the neuroprotective effects of PNS against cerebral ischemia injury." (PMID 35770087, 2022). "Meanwhile, upregulation of BDNF expression and activation of Akt/mTOR/p70S6K signaling after ME could partially underlie the neuroprotective effects of PNS against cerebral ischemia injury." (PMID 35770087, 2022). "Meanwhile, upregulation of brain-derived neurotrophic factor (BDNF) expression and activation of Akt/mTOR/p70S6K signaling after ME could partially underlie the neuroprotective effects of PNS against cerebral ischemia injury." (PMID 35770087, 2022). "Meanwhile, BDNF upregulation and activation of Akt/mTOR/p70S6K pathway could partially underlie the neuroprotective effects of PNS against cerebral ischemia injury." (PMID 35770087, 2022). "The aim of this study was to determine whether the daidzein elicits beneficial actions in a stroke model, namely, cerebral ischemia/reperfusion (I/R) injury, and to reveal the underlying neuroprotective mechanisms associated with the regulation of Akt/mTOR/BDNF signal pathway." (PMID 35095491, 2021). "Therefore, we speculate that mTOR/autophagy-associated pathways play an important role in the pathological process of the aggravation of cerebral ischemia nerve injury caused by intermittent hypoxia." (PMID 28177899, 2017). "IU1 can have several pleiotropic effects through the regulation of known UPS targets (e.g. mTOR), and more importantly, through the regulation of autophagy, all of them known to have an impact in neuronal survival in several models of brain ischemia." (PMID 40095265, 2025). "Intranasal administration of recombinant human SESN2 (rh‐SESN2) provides neuroprotective effects in hypoxic–ischemic encephalopathy by conditioning the AMPK/mTOR pathway in rat newborns." (PMID 40032632, 2025). "Mechanistically, TIGAR partially inhibits autophagy by decreasing ROS and activating the mTOR-S6K pathway, thereby preventing cerebral ischemia-induced neuronal injury." (PMID 37856037, 2024). "In vitro and in vivo models of cerebral ischemia, in addition to mTOR and NLRP3 inflammasome, PRNP, sphingosine kinase 1 (SphK1), DJ-1 and other signals participate in the regulation of neuroinflammation through autophagy as well." (PMID 37548945, 2024). "In this study, we have evaluated the role of mTOR activity after cerebral ischemia focusing on microglial response during the acute phase, by using the mTOR inhibitor rapamycin." (PMID 38582839, 2024).
Cerebral ischemia (continued). "Here, we studied the role of mammalian target of rapamycin (mTOR) activity in the microglial response using a murine model of cerebral ischemia in the acute phase." (PMID 38582839, 2024). "Consistent with the findings of these previous studies, we found that epalrestat mediates the mTOR pathway in BMVECs after cerebral ischemia and inhibits autophagy and apoptosis." (PMID 36940077, 2023). "To date, studies have found that targeted inhibition or activation of the mTOR signaling pathway is an effective way to regulate neuronal apoptosis in the process of cerebral ischemia." (PMID 36940077, 2023). "While there is extensive information about the role of astrocytes after cerebral ischemia, few studies have described the participation of mTOR activity in this context." (PMID 35269956, 2022). "Knockout of NF-κB p50 subunit in mice can promote autophagy via inhibiting mTOR pathway after cerebral ischemia." (PMID 35109896, 2022). "In this present study, p-AMPK protein levels were increased and p-mTOR protein levels were decreased after acute cerebral ischemia, and OGD/R-ADEX reversed the expression levels of these proteins." (PMID 36539418, 2022). "In summary, we have demonstrated that cornin plays neuroprotective effect after cerebral ischemia injury in SD rats by preventing astrocytes autophagy induced by CI/R via the PI3K/Akt/mTOR signaling pathway." (PMID 36280856, 2022). "Previous studies showed that PI3K/Akt/mTOR signaling is essential to the survival of neurovascular units cerebral ischemia." (PMID 36280856, 2022). "Several studies have shown that mTOR plays a key role in neuroprotection activated by EA in cerebral ischemia and the AKT-mTOR-S6 signaling axis has an important functional role in the intrinsic mechanisms of axonal regeneration." (PMID 36440366, 2022). "It is concluded that SIK2 can ameliorate neuronal injury and promote the energy metabolism by regulating the mTOR pathway during cerebral ischemia-reperfusion, and this process is related to mitochondrial autophagy." (PMID 35586047, 2022). "So we conclude that SIK2 can improve the mitochondrial autophagy restriction which is induced by cerebral ischemia-reperfusion to promote the occurrence of energy metabolism through the mTOR pathway in rats." (PMID 35586047, 2022). "Some researchers have reported that EA improves learning and memory functions by upregulating the expression of mTOR in rats with vascular dementia or cerebral ischemia/reperfusion, and MSCs affect mTOR signaling through paracrine effects or exosomes." (PMID 35211177, 2022). "Activation of the PI3K/Akt/mTOR pathway inhibits the occurrence of autophagy, which is essential for the growth and survival of neurons after cerebral ischemia." (PMID 35111232, 2022). "It has been reported that the TCM prescription Tong-Qiao-Huo-Xue decoction can activate PI3K/Akt/mTOR signaling pathway to reduce brain microvascular endothelial cell (BMECs) autophagy after cerebral ischemia/reperfusion injury." (PMID 36432062, 2022). "Previous investigations have shown that mTOR-mediated signaling pathway PI3K/RAC-α serine/Akt/mTOR controls autophagy in cerebral ischemia." (PMID 36280856, 2022). "It is noteworthy that the basal extent of mTOR activation is decreased in both severe acute pancreatitis and cerebral ischemia." (PMID 35003304, 2021). "Using rapamycin, a first-generation mTOR inhibitor, we have demonstrated the aggravation of cerebral ischemia at 2 h of reperfusion after 1 h of middle cerebral artery occlusion (MCAO)." (PMID 34354602, 2021). "Accumulating evidence demonstrates that the AKT/mTOR signalling pathway can modulate neuroprotective activation following cerebral ischemia-reperfusion (I/R)." (PMID 35095491, 2021). "It has been reported that the mechanistic target of rapamycin (mTOR) pathway is involved in cerebral ischemia–reperfusion injury." (PMID 34354602, 2021).
Cerebral ischemia (continued). "It reduced stimulator of interferon gene (STING) activity and regulated mTOR to inhibit autophagy and induce cerebral ischemia tolerance." (PMID 34406977, 2021). "Paradoxically, mTOR inhibition can either improve or aggravate the brain infarct size following cerebral ischemia in rats." (PMID 34226528, 2021). "There are studies suggesting the involvement of mTOR pathway in altering BBB disruption in cerebral ischemia–reperfusion." (PMID 34354602, 2021). "As a negative regulatory element of autophagy induction, phosphorylation of the PI3K/Akt/mTOR signaling pathway is always impaired during cerebral ischemia/reperfusion." (PMID 34815829, 2021). "The in vivo and vitro results thus reveal that DOR activation by DADLE enhances neuronal autophagy to protect against cerebral ischemia by activating the AMPK/mTOR/ULK1 signaling pathway." (PMID 32549974, 2020). "Curcumin provides neuroprotection in in vivo models of traumatic brain injury and cerebral ischemia-reperfusion via p-Akt and p-mTOR (mammalian target of rapamycin) and the Nrf2-ARE (antioxidant response element) signaling pathways." (PMID 32867057, 2020). "A previous study has reported that curcumin exerts neuroprotective effects in cerebral ischemia-reperfusion by attenuating autophagic activities through mediating the PI3K/Akt/mTOR pathway." (PMID 33204708, 2020). "Accumulating evidence demonstrates that the AMPK/mTOR signaling pathway can modulate autophagic activation following cerebral ischemia-reperfusion (I/R)." (PMID 31597329, 2019). "In our previous studies, we have utilized a transient global cerebral ischemia model in rats to examine the correlations between mTOR signaling and neuronal cell death during fixed reperfusion intervals." (PMID 30594149, 2018). "Two recent studies suggested that neuron and microglia or macrophage-derived FGF10 participates in activation of PI3K/AKT/mTOR, which contributes to either ameliorate cerebral ischemia injury or improve functional recovery after spinal cord injury." (PMID 30532765, 2018). "Mechanistically, the better recovery of skeletal muscle mass in MCAO mice receiving PINTA745 cannot be explained by a specific regulation of IGF-1-Akt-mTOR pathway and autophagy-lysosome system 15 days after cerebral ischemia." (PMID 29070788, 2017). "In conclusion, intermittent hypoxia can aggravate the nerve injury of global cerebral ischemia-reperfusion via activating mTOR/autophagy pathway." (PMID 28177899, 2017). "Based on experimental results, EA pretreatment significantly suppressed mTOR activity during cerebral ischemia, mainly manifested as the decrease of the phosphorylation of 2448 and (or) 2481 serine loci of mTOR." (PMID 27547233, 2016). "Activation of the PI3K/Akt/mTOR pathway plays an essential mechanism for maintaining cellular homeostasis when responding to focal cerebral ischemia." (PMID 25954164, 2015). "During cerebral ischemia, the Akt/mTOR pathway is activated in response to hypoxia and mediates activation or stabilization of hypoxia-inducible factor-1 alpha (HIF-1)." (PMID 24771476, 2014). "Furthermore, studies have demonstrated that trigonelline inhibits autophagy via the PI3K/AKT/mTOR signaling pathway, thereby mitigating cerebral ischemia-reperfusion pyroptosis." (PMID 40491449, 2025). "Notably, in mouse models, the knockout of the NF-κB p50 subunit has been observed to promote autophagy by inhibiting the mTOR pathway after cerebral ischemia." (PMID 39846000, 2024). "Furthermore, lithium chloride demonstrates the capacity to activate mTOR, restraining excessive autophagy and consequently ameliorating spatial cognitive deficits in murine models of cerebral ischemia-reperfusion." (PMID 38169754, 2024). "Collectively, these data underscore that GABAAR activation may confer neuroprotection during cerebral ischemia by inhibiting autophagy via the AMPK/mTOR signaling pathway." (PMID 38397792, 2024).